KRAS (KRas proto-oncogene, GTPase)
Diseases named in the same sentence as KRAS in open-access papers (continued):
Sharing a sentence is not in itself a finding about the gene and the disease.
tumor (continued). "When we compared the differences between normal and tumor tissues, in most tumor tissues the expression levels of KRAS were higher than normal tissues." (PMID 36330448, 2022). "KRAS and NRAS mutation status prevalence was as expected in the first-line setting, as were tumor location and microsatellite stability status." (PMID 36029653, 2022). "The extensive literature describing the role of mutant KRAS in proliferation, survival, metabolism and motility supports its significant role in tumour aggressiveness, metastasis and resistance to chemotherapy." (PMID 36163168, 2022). "Nonetheless, it did not produce CARs with sufficient functional activity to mediate strong cytotoxicity in unmodified mutant KRAS-positive tumor cell lines." (PMID 36860694, 2022). "This study also has found that β-elemene also inhibits epithelial-mesenchymal transformation (EMT) by inhibiting metastasis of KRAS-mutant colon cancer tumor cells." (PMID 36193068, 2022). "Tumor markers included BRAF and KRAS mutations, microsatellite instability and CpG island methylator phenotype." (PMID 35383926, 2022). "The interaction of these complexes with KRAS G-quadruplex DNA was studied by spectroscopy and molecular docking simulations, and their inhibitory activity against various human tumor cells was evaluated by MTT assay." (PMID 35630522, 2022). "KRAS G12D was also most common among many other tumor types including PDAC (43%), and endometrial (30%), and KRAS G12V was the second most common in the majority of tumor types studied and the most common KRASm in breast (26%)." (PMID 36494601, 2022). "MRTX849 is a potent and selective KRAS G12C inhibitor, achieving 65% tumor regression in vitro and in patient-derived xenograft models." (PMID 36139444, 2022). "The activation of mutant KRAS was shown to foster tumor growth by rewiring cancer cell metabolic pathways, which was initially revealed by its ability to promote glycolysis." (PMID 35681705, 2022). "Apparently, the addiction and dependence of KRAS mutant tumor cells on macropinocytosis lay the theoretical basis for obtaining therapeutic benefits by inhibiting macropinocytosis." (PMID 35154489, 2022). "Splenocytes subsets were similar to tumor-naive controls with only MOE-PTEN/KRAS showing different proportions of immune cells compared with FVB/N control spleens." (PMID 36311166, 2022). "We established 22 cell expression datasets based on the immune-infiltrating levels to explore the potential effect of KRAS expression levels on the tumor immune cell infiltration." (PMID 36330448, 2022). "Mutant KRAS induces the monocyte to become the tumor-promoting phenotype (M2 type) through secreting many factors to elicit polarization in macrophages." (PMID 35252207, 2022). "The model well captured the reported time curves of tumor sizes and mutant KRAS levels in ctDNA from mCRC patients." (PMID 35273301, 2022). "Concomitant driver mutations included activating mutations in classic oncogenes (e.g., KRAS, NRAS, EGFR, and PIK3CA), as well as loss-of-function mutations in tumor suppressors (e.g., BRCA1/2 and PTEN)." (PMID 36369474, 2022). "Our study emphasizes the importance of considering the assessment of tumour characteristics by the TBS score within a KRAS evaluation in synchronous and aggressive CRC, looking towards a lower recurrence and longer survival." (PMID 35326950, 2022).
tumor (continued). "In our study, the high Fn levels of cancer tissue were associated with key tumor molecular features of CRC, including MLH1 methylation, MSI-high, CIMP-high, KRAS mutation, and BRAF mutation, which were associated with clinical outcomes in CRC." (PMID 36406461, 2022). "IL-4 and IL-13 have both been shown to supress the anti-tumoural immune response, and moreover to directly drive the proliferation of KRAS-mutant tumour cells." (PMID 36010845, 2022). "Activation of ERBB2 signaling enhances tumor growth and can act synergistically with KRAS to promote the aggressiveness of PC cells." (PMID 35588577, 2022). "In summary, we demonstrated that HOXA7 overexpression upregulated CXCL1 expression, facilitating the recruitment and infiltration of MDSCs into the KRAS mutant CRC tumor niche." (PMID 35183163, 2022). "The lower success rate of mutation-matched therapies in PDAC compared to other tumor types is frequently attributed to the concurrent activation of KRAS or to the unique PDAC tumor microenvironment (TME)." (PMID 36077755, 2022). "These genes all have different functions and effects: KRAS is a tumor-specific mutation that promotes the initiation and progression of cancers, and STK11 is a tumor suppressor that loses function after mutations." (PMID 35159000, 2022). "The CAM assay was performed to evaluate tumor growth of H292 KRAS mutant cell lines, and we found a significant increase in tumor perimeter of both KRAS mutant cells, compared to wild-type." (PMID 35887120, 2022). "The results presented above demonstrate the ability of KRASG12C inhibitors to reverse KRAS-driven immune evasion mechanisms, such as enhancing tumor cell–intrinsic IFN responses and modulating the expression of secreted immunomodulatory factors." (PMID 35857848, 2022). "POLE ultra-mutated tumours exhibit few copy number aberrations and have mutations in PTEN, PIK3RI, PIK3CA, FBXW7 and KRAS genes." (PMID 35530346, 2022). "Bolivar and colleagues found a significant association between the presence of plasma ctDNA mutation (CTNNBI, KRAS, PTEN, or PIK3C) and advanced stage, deep myometrial invasion, LVSI, and primary tumour size." (PMID 35530346, 2022). "After optimization, the method was applied for the genotyping of the KRAS gene in cell-free DNA and circulating tumor DNA in blood samples from healthy individuals and CRC patients with known mutations." (PMID 35200357, 2022). "Together, these indicated that silencing Fbxo45 played additive effects with Afatinib on suppressing the tumor growth of H1975 cells, even though harboring EGFR‐T790M resistance mutation and KRAS mutation, in vitro and in vivo." (PMID 35838331, 2022). "In fact, MDA-MB-231 and A549 cells used in our experiments also bear KRas mutations, and we show that knockdown of either EGFR or ARF6 inhibits tumor growth." (PMID 36224181, 2022). "Several preclinical studies demonstrated that adagrasib in combination with SHP2 inhibitors led to tumor regression in several KRAS G12C mutant patient-derived and cell line xenograft models." (PMID 36508072, 2022). "Further, let-7b has lower activation in neoplastic bronchus and lung, which is a known tumour-suppressor and has been shown to target KRAS." (PMID 35026982, 2022).
tumor (continued). "EGFR mutation is usually connected with low PD-L1 expression, while KRAS and MET alterations are associated with higher PD-L1 tumour expression." (PMID 35329956, 2022). "Several tumor-related markers, including the KRAS signaling pathway, IL-6/JAK/STAT3 signaling pathway, and inflammatory response were identified, which were enriched in low-risk patients." (PMID 36244998, 2022). "We also show that a high proportion of KRAS wild-type tumours do exhibit the characteristics of RAS pathway activation." (PMID 36163168, 2022). "The gold dashed line represents the patients with KRAS and BRAF wild-type (double wt) tumours and the black dashed/dotted line represents the BRAF-mutated microsatellite instable (MSI (mutBRAF/MSI) tumours." (PMID 34887523, 2022). "At the molecular level, these tumor characteristic mutations included PTEN (88%), RPL22 (33%), KRAS (35%), PIK3CA (54%), PIK3R1 (40%), and ARID1A (37%) with high TMB levels (18 × 106 Muts/Mb) and certain TIL." (PMID 36578004, 2022). "On the other hand, two patients had KRAS WT tumor in the metastatic tissue and KRAS MT tumor (one patient had KRASG13C and one patient had KRASG12D) in the primary tissue." (PMID 35592200, 2022). "Tumor mutations identified included BRAFV600E in 27 (54%), MAP2K1 in 6 (12%), KRAS in 3 (6%), non-V600 BRAF in 3 (6%), and others." (PMID 33057928, 2021). "Patients with a KRAS p.G12R mutated tumor tended to have a prolonged disease‐free survival (DFS) and overall survival (OS) than other KRAS subtypes." (PMID 33350171, 2021). "One study showed that KRAS gene mutations existed in approximately 25% of the tumor tissues of TKI-insensitive patients, and another randomized controlled study showed that KRAS gene mutations were one of the factors influencing the efficacy of TKIs." (PMID 34575576, 2021). "For example, three amino acid residues (G12, G13, and Q61) in HRAS, KRAS, and NRAS are mutational hot spots, though with distinct frequencies in different human tumor types." (PMID 34607583, 2021). "While deeper genomic sequencing was outside of the scope of this study, interrogation of our KRAS wild-type tumours for other genetic drivers would be extremely valuable in evaluating the lack of response to EGFR inhibition in our patient cohort." (PMID 34956889, 2021). "PDL-1 (a key target for immune checkpoint blockade) expression was reduced in mice tumours via the PAK-1-dependent pathway (p-21 activated kinase 1) activated by Kirsten rat sarcoma (KRAS)." (PMID 34259916, 2021). "The effects of KRAS signaling in the tumor microenvironment of solid tumors have been extensively studied, but the role of KRAS in modulating the ECM remains poorly understood." (PMID 33817986, 2021). "A biopsy of the original tumor was sent for panel-based genomic testing in 2019 which identified the tumor as KRAS WT, NRAS WT, BRAF WT (Caris, Irving, TX, USA)." (PMID 34504655, 2021). "The HDI romidepsin was able to improve erlotinib anti-tumour effect in nine NSCLC lines with varying histology and mutation conditions, including EGFR-, KRAS-mutant, and wild type cell lines, with a decrease in tumour load in NCI-H1299 xenograft models." (PMID 34769131, 2021). "It was recently highlighted that KRAS-mutant tumors are a very heterogeneous disease, including different tumor subtypes with variable biological backgrounds, different prognoses, and clinical responses to immunotherapy." (PMID 34831355, 2021). "Treatment with EMICORON, a synthetic compound binding to G4 structures, downregulated KRAS mRNA and protein expression in CRC cell lines, and decreased tumor volume in patient-derived xenografts bearing KRAS mutation." (PMID 34064352, 2021). "Although it is known that c-MYC is a crucial downstream effector of oncogenic KRAS in other tumor types, the biological importance of this transcription factor in PDAC had not been acknowledged until recently." (PMID 34491463, 2021).
tumor (continued). "Upregulated genes expressed in type 3 ductal cells were mainly mediated in tumor migration-related processes like Wnt/β-catenin and KRAS signaling pathways, indicating that type 3 ductal cells were identified as cells of relatively high malignancy." (PMID 34732701, 2021). "NS1 however, was effective at inhibiting KRAS-driven tumor formation in mouse models, suggesting that blocking a larger surface area of this interface is necessary to modulate KRAS signaling." (PMID 33802474, 2021). "The group developed a PEGylated lipid-based nanoparticle named LNPK15 using two novel cationic lipids, SST-01 and SST-31, encapsulating KRAS siRNA that showed long circulation and efficient siRNA delivery to tumor sites." (PMID 34683931, 2021). "PTEN deletion allows the cells to remain dormant in vivo, while KRas activation leads to dormancy or, rarely, to tumor formation." (PMID 33986306, 2021). "KRAS mutant tumors are characterized by enabling tumor cells to escape immunosurveillance as one of the hallmarks of cancer." (PMID 35096591, 2021). "Silencing HIF-1α was found to significantly suppress the production of CSF2 and lactate in KRAS mutant tumor cells, abrogating the ability to induce TAM-like changes in macrophages." (PMID 33833221, 2021). "Epithelial-to-mesenchymal transition (EMT) in tumor cells is also a characteristic phenotype of KRAS independency." (PMID 34680229, 2021). "These GAP isoforms lost their function to contact and inactivate mutant KRAS, so KRAS downstream signaling pathways are turned on and contribute to tumor growth." (PMID 34439241, 2021). "When KRAS-targeting siRNA is formulated in this delivery vector and peritumorally injected in pancreatic xenograft models, significant decreases in tumor growth and local invasion were observed." (PMID 34683931, 2021). "It is known that KRAS can initiate tumor progression and formation of early-stage PanIN, whereas the absence of functional MYC prevents transition to PDAC." (PMID 34947972, 2021). "It is notable that HLALOH occurred in the samples with recurrent mutations of S-C clonal pattern including KRAS, SYNE1, FBXL2, DNAH11 and CACNA1H, indicating this mutational clonal patter is facilitating tumor cell to escape immune monitor." (PMID 34453042, 2021). "Mutant KRAS proteins are insensitive to GAP-induced GTP hydrolysis, which is linked to many aspects of tumor initiation and progression, including deregulation of key signal transduction pathways, altered metabolism, metastasis and drug resistance." (PMID 34336638, 2021). "Array CGH was performed for these four cases with the same mutation profiling among paired tumours by NGS and for three cases (Cases 3, 15 and 17) with the same driver mutations that included EGFR or KRAS mutations." (PMID 33707471, 2021). "The potential use of let-7 as a chemo-sensitizer has also emerged in KRAS mutant NSCLC cells, in which let-7b repletion selectively sensitized KRAS mutant tumor cells to paclitaxel and gemcitabine by diminishing MEK/ERK and PI3K/AKT signaling." (PMID 34771690, 2021). "KRAS abnormal tumor cells can switch the tumor immune microenvironment from an antitumorigenic to a pro-tumorigenic." (PMID 35186946, 2021). "This analysis of KRAS genetic networks in four different tumor types highlights the tissue-specific nature of genetic interactions." (PMID 33753749, 2021).
tumor (continued). "These KRAS-independent tumor cells exhibit a mesenchymal phenotype, readily primed for potential metastasis." (PMID 34680229, 2021). "There is growing evidence that oncogenic KRAS is involved in tumor immune evasion by regulating the TME." (PMID 34885068, 2021). "Mutations which activate members of the RAS family (KRAS, HRAS, and NRAS) can be found in as much as 20–30% of all human tumours." (PMID 33925206, 2021). "Regional differences were also observed concerning the impact of tumor sidedness on treatment decisions for patients with mCRC and KRAS wildtype." (PMID 34199694, 2021). "Considering the effect of MSI on the tumor microenvironment, we analyzed the TIL density according to the KRAS mutations in MSS/MSI-L or MSI-H CRCs." (PMID 34272423, 2021). "Our observation that tumor cells can survive knockout of oncogenic KRAS and retain tumorigenic capacity likewise suggests that KRAS reprograms cells to a stably transformed state that no longer depends on continuous KRAS expression." (PMID 33674596, 2021). "Of these, the RAS–MAPK constitutes the most frequently affected pathway: up to 90–95% of PC present with activating KRAS mutations and alternative RAS-MAPK pathway alterations are seen in ≈60% of KRAS wild-type tumours." (PMID 33406790, 2021). "The ability of mutant KRAS to modulate tumor immunity highlights the importance of adopting a combinatorial treatment approach with KRAS inhibition and simultaneous stimulation of the immune system." (PMID 34957115, 2021). "In CRC context, some studies demonstrated that oncogenic KRAS is able to reduce the expression of IFNγ targeted genes in KRASMUT tumor cells (HCT-116 cells with KRASG13D), including STAT1 and MHC-II." (PMID 33691728, 2021). "CRC development is driven by Wnt/Myc hyperactivation, KRAS/BRAF mutation, genetic instability and accompanied by progressive immunosuppressive tumor microenvironment (TME)." (PMID 34221955, 2021). "Sod1 knockout markedly reduces tumor burden in vivo and blocks growth of KRAS mutant NSCLC cells in vitro." (PMID 33859191, 2021). "For example, KRAS mutant tumours upregulate the amino acid transporter SLC7A5 in order to meet the increased demand for protein synthesis allied with rapid cancer cell proliferation." (PMID 34944851, 2021). "Overall, authors concluded that KRAS initiates cancer development, but at advanced stages immune system suppression takes over the role for tumor progression, thereby leaving the tumor KRAS independent." (PMID 34781949, 2021). "Given this complexity, determining the role of individual genes in the TGF-beta pathway and KRAS tumor immunity will require further research." (PMID 33674596, 2021). "Data from colorectal patients showed a significant inverse correlation between expression of MST2 and mutant KRAS, and in the few instances where these proteins were co-expressed, the tumours had high apoptosis rates." (PMID 33920182, 2021). "Our study also demonstrates the high concordance of ctDNA and tumour tissues for the molecular characterisation (KRAS and BRAF status), which was shown in many previous studies." (PMID 34294055, 2021). "The result of these heterocellular reciprocal interactions is that oncogenic KRAS signalling bypasses “tumor cell only” signalling, potentiating further tumorigenesis." (PMID 34298706, 2021). "Genetic mutations of KRAS, copy number deletion of 3p21.1, and activated EMT process enhance the metastatic ability of primary tumor cells." (PMID 33397441, 2021). "For example, combined mTOR and HDAC inhibitors resulted in tumor regression in a mice xenografts models of KRAS-mutant NSCLC in vivo." (PMID 34301278, 2021). "Our results indicated that miR-1184 promotes tumor progression by directly targeting KRAS/NRAS/HRAS in UBC." (PMID 34234808, 2021).